TIGIT (T cell immunoreceptor with Ig and ITIM domains)
Diseases named in the same sentence as TIGIT in open-access papers (continued):
Sharing a sentence is not in itself a finding about the gene and the disease.
tuberculosis (2 papers, 2025). A chronic, recurrent infection caused by the bacterium Mycobacterium tuberculosis. "Moreover, multiple genes encoding NK receptor and cytotoxic granules associated with NK-like cytotoxicity and anti-tuberculosis effector function were more highly expressed in TIGIT+PD-1− cells." (PMID 40526725, 2025). "Our results support a close correlation between TIGIT and the activation of anti-tuberculosis immunity and disease severity of ATB patients." (PMID 40526725, 2025). "This is, to our knowledge, the first data on the effect of in vivo TIGIT blockade in a mouse model of tuberculosis." (PMID 40526725, 2025). "Such a transcriptional signature indicated that TIGIT+CD8+ T cells possess the capacity to produce anti-tuberculosis effector molecules and phenotypic features similar to NK cells, instead of being functionally exhausted, in individuals with ATB." (PMID 40526725, 2025). "Our findings advance the knowledge of the regulatory role of TIGIT in the T cell-mediated immune response to tuberculosis, and have implications for immune intervention in tuberculosis." (PMID 40526725, 2025). "To determine how TIGIT affect host anti-tuberculosis immune response, we next assessed the effect of in vitro TIGIT blockade on the functions of CD8+ T cells from individuals with ATB." (PMID 40526725, 2025). "In combination with our phenotypical, transcriptional and TIGIT blockade assay results, TIGIT seems to be an activation marker with regulatory effect in the context of active tuberculosis." (PMID 40526725, 2025). "The findings also suggest that TIGIT limits T cell immunity in tuberculosis and implicate TIGIT blockade as a novel strategy for tuberculosis therapy." (PMID 40526725, 2025). "Together, these results revealed an upregulated expression of TIGIT in both peripheral blood and lung lesions during active tuberculosis." (PMID 40526725, 2025). "Our data showed that in active tuberculosis patients, TIGIT expression on peripheral CD8+ T cells upregulated significantly and correlated with more severe disease." (PMID 40526725, 2025). "Our results support the negative regulatory role of TIGIT in CD8+ T cell mediated immunity against tuberculosis and demonstrate the promoting effect of TIGIT blockade on the immune response to tuberculosis." (PMID 40526725, 2025). "The findings reveal that in active tuberculosis patients activated CD8+ T cells express TIGIT and blocking TIGIT enhances CD8+ T cell function and promotes clearance of M. tuberculosis." (PMID 40526725, 2025). "In active tuberculosis patients, TIGIT expression on CD8+ T cells in the peripheral blood was significantly upregulated and positively correlated with disease severity." (PMID 40526725, 2025). "Here, we report for the first time the expression of TIGIT in lung lesions from individuals with tuberculosis." (PMID 40526725, 2025). "TIGIT blockade could promote anti-tuberculosis immunity in vitro and clearance of MTB infection in vivo." (PMID 40526725, 2025). "However, how TIGIT participates in the pathogenesis of tuberculosis is unclear." (PMID 40526725, 2025). "The functional status of TIGIT+ and TIGIT−CD8+ T cell subsets in tuberculosis patients was analyzed by flow cytometry and transcriptome analysis." (PMID 40526725, 2025). "TIGIT blockade improved the proliferation and clearance of intracellular infected BCG in vitro, and enhanced the control of MTB infection in a mouse model of tuberculosis." (PMID 40526725, 2025).
acute coronary syndrome (1 paper, 2025). Signs and symptoms related to acute ischemia of the myocardium secondary to coronary artery disease. "first revealed through flow cytometry that TIGIT+ regulatory T cells (TIGIT+Tregs) in patients with acute coronary syndrome (ACS) are significantly reduced (significantly lower than in patients with chronic coronary syndrome (CCS) and healthy controls, P<0.05)." (PMID 40821806, 2025).
Acute hepatitis (1 paper, 2024). Acute hepatic injury resulting from inflammation typically accompanied by increased serum alanine transaminase activity. "Blocking TIGIT by antibody or genetic knockout enhanced NK cell activation and aggravated liver injury in a poly I:C/D-GalN-induced model of acute hepatitis." (PMID 38545097, 2024).
allergic asthma (1 paper, 2018). A asthma with a basis in a pathological type I hypersensitivity reaction. "Consistent with the results of a previous study, which showed increased TIGIT expression in the MLNs of mice with Th2‐driven allergic asthma, we observed that TIGIT expression was elevated in the MLNs of mice with allergic asthma." (PMID 29512870, 2018). "The increase in TIGIT expression and its attenuation by DW2008S in mice with allergic asthma appear to be limited to FOXP3− effector T cells, which seems to mostly result from fluctuations in number of TIGIT+ IL‐4+ Th2 cells." (PMID 29512870, 2018). "The results indicate that DW2008S may ameliorate allergic asthma through regulation of TIGIT expression in Th2 cells rather than in Tregs." (PMID 29512870, 2018). "However, the number of MLN FOXP3+ Tregs, including TIGIT+ Tregs, in the mice with allergic asthma did not increase compared to the number in the normal mice." (PMID 29512870, 2018).
anaphylaxis (1 paper, 2023). An acute hypersensitivity reaction that occurs from exposure to an allergen. "In severe airway anaphylaxis, a group of TIGIT+IL-10+ILC2 was identified as seemingly “exhausted” cells since they expressed the inhibitory receptor, TIGIT, characteristic of exhausted CD8+ T cells." (PMID 37947634, 2023).
anemia (1 paper, 2025). A reduction in the number of red blood cells, the amount of hemoglobin, and/or the volume of packed red blood cells. "In addition, anti-TIGIT–treated mice with NK depletion experienced anemia, thrombocytopenia, and leukocytosis comparable to isotype control-treated mice." (PMID 40111422, 2025).
aneuploidy (1 paper, 2025). Chromosomal disorder consisting of the presence a chromosomal abnormality in which there is an addition or loss of chromosomes within a set. "In addition, it was also found that some immune checkpoint genes (PDCD1, HAVCR2, TIGIT, LAG3) had high expression in high-risk group, which was related to a higher TIDE and aneuploidy scores than in the low-risk group." (PMID 39950044, 2025).
aortic aneurysm (1 paper, 2022). A ruptured aneurysm located in the wall of the proximal portion of the descending aorta proceeding from the arch of the aorta. "FOXP3+ Treg cells were abundant in aortic aneurysms, especially in AAA groups and displayed high expression of exhausted genes CTLA4, TIGIT, TNFRSF14, ICOS, and CD28." (PMID 36703732, 2022).
aplastic anaemia (1 paper, 2023). "Indeed, MEG3, a long non-coding RNA can modulate TIGIT expression on CD4+ T cells from aplastic anaemia patients." (PMID 38077329, 2023).
Ascites (1 paper, 2021). Accumulation of fluid in the peritoneal cavity (between the layers of the peritoneum that lines the abdomen). "We also evaluate the effect of VV-α-TIGIT on immune-cell infiltration and activation in another H22 ascites tumor model in BALB/c mice." (PMID 33581644, 2021).
astrocytomas (1 paper, 2024). "Our study showed that CD47 and TIGIT expression levels in GBM were significantly higher than in astrocytomas and oligodendrogliomas." (PMID 38404571, 2024). "High expression of CD47, TIGIT, and CD47/TIGIT was all associated with poor survival in ADG and GBM, whereas high expression of CD47 was associated with shorter OS in astrocytoma." (PMID 38404571, 2024). "Unmethylated MGMT in astrocytomas and the overexpression of CD47 and TIGIT in ADG tissues are associated with a poor prognosis." (PMID 38404571, 2024). "Dual CD47/TIGIT high expression was not correlated with age, sex, astrocytoma of all grades, or pTERT mutations." (PMID 38404571, 2024). "High CD47 expression, but not TIGIT and CD47/TIGIT, significantly reduced the OS of patients with astrocytoma (P < 0.05)." (PMID 38404571, 2024).
autoimmune uveitis (1 paper, 2022). An autoimmune form of uveitis (disease). "The increased expression of TIGIT is associated with hypomethylation and FOXP3 binding at the locus of TIGIT, and TIGIT+ Tregs contributed to the remission of autoimmune uveitis." (PMID 35720417, 2022).
cervical disease (1 paper, 2021). "What stood out in the tables was the patients afflicted with the cervical disease showed positive correlation significantly, such as famous immune checkpoint genes (CTLA4, TIGIT, HAVCR2, LAG3, etc.)and costimulatory genes like ICOS, CD80, CD40, and so forth." (PMID 33694292, 2021).
cervical tumours (1 paper, 2022). "In WT-U14 injected C57BL/6 mice, the blocking TIGIT inhibited the growth and proliferation of cervical tumours." (PMID 35729552, 2022).
chordoma (1 paper, 2022). Chordomas are rare malignant tumors arising from embryonic remnants of the notochord in axial skeleton. "The effects of many immune checkpoints, including LAG3, TIM3, SIRPα, HHLA2, MAGEA4, VISTA and TIGIT, have been validated in chordoma, and five of them (TIM3, SIRPα, HHLA2, MAGEA4 and VISTA) were only evaluated in preclinical study." (PMID 36612259, 2022).
Chronic colitis (1 paper, 2022). A chronic inflammatory disease of the large intestine (colon, cecum and rectum). "In a dextran sulfate sodium (DSS)-induced chronic colitis mouse model, significantly lower frequencies of TIGIT+ Tregs were found in spleen, mesenteric lymph node (MLN), lamina propria mononuclear cells (LPMC), and colonic intraepithelial lymphocytes (IEL) compared to the control groups." (PMID 35720417, 2022). "Moreover, treatment with ERβ agonist ERB041 could significantly restore the frequency of TIGIT+ Tregs and alleviate DSS-induced chronic colitis and inflammation in mouse models, implicating the potential roles of TIGIT expressed on Tregs during the development of chronic colitis." (PMID 35720417, 2022).
chronic hepatitis B (1 paper, 2021). "The expression of TIGIT in NK cells of patients with immune active chronic hepatitis B is lower than normal, and the level of TIGIT correlated inversely with NK-cell function in chronic HBV." (PMID 35265633, 2021).
classic Hodgkin lymphoma (1 paper, 2022). Classical Hodgkin lymphoma (CHL) is a B-cell lymphoma characterized histologically by the presence of large mononuclear Hodgkin cells and multinucleated Reed-Sternberg (HRS) cells. "Furthermore, TIGIT was similarly up-regulated in classic Hodgkin lymphoma (cHL) and Sezary syndrome." (PMID 36605439, 2022).
co-infection (1 paper, 2020). "SIV and Mtb co-infection led to increased expression of the activation/exhaustion markers PD-1 and TIGIT, and decreased ability to secrete TNFα when compared to SIV-naïve MCM." (PMID 32433713, 2020).
cutaneous T-cell lymphoma (1 paper, 2023). "They discovered that TIGIT was present on tumor cells in hematologic cancers such as cutaneous T-cell lymphoma." (PMID 36765704, 2023). "Anti-TIGIT antibody efficacy is yet to be evaluated in patients with cutaneous T-cell lymphoma." (PMID 36765704, 2023).
depression (1 paper, 2022). "The expression level of 100A12, SERPINB2, GRB10, and LHFPL2 was higher in the depression group, whereas TIGIT showed a high expression profile in the normal control group." (PMID 36325528, 2022). "The genes S100A12, TIGIT, SERPINB2, GRB10, and LHFPL2 in peripheral serum are viable diagnostic biomarkers for depression." (PMID 36325528, 2022). "ROC analysis based on both GSE98793 and GSE76826 datasets suggested that S100A12, TIGIT, SERPINB2, GRB10, and LHFPL2 in the peripheral serum have the potential to act as diagnostic biomarkers for depression." (PMID 36325528, 2022). "S100A12, TIGIT, SERPINB2, GRB10, and LHFPL2 identified as potential diagnostic biomarkers in peripheral blood of patients with depression using three machine learning algorithms." (PMID 36325528, 2022). "Subsequently, S100A12, TIGIT, SERPINB2, GRB10, and LHFPL2 in peripheral blood were identified as Potential diagnostic biomarkers in peripheral blood for depression by SVM–REF, Random forest, and LASSO algorithms." (PMID 36325528, 2022). "Based on the results of the ROC (validation set AUC value > 0.7) analysis in the current study, S100A12, TIGIT, SERPINB2, GRB10, and LHFPL2 may possess potential as diagnostic biomarkers of depression." (PMID 36325528, 2022). "We further investigated the role of S100A12, TIGIT, SERPINB2, GRB10, and LHFPL2 in depression and observed their expression profiles in patients." (PMID 36325528, 2022). "Among them, the relevance scores of S100A12, TIGIT, SERPINB2, GRB10, and LHFPL2 with depression were 4.356, 4.232, 3.064, 1.516, and 0.698, respectively." (PMID 36325528, 2022). "Subsequently, the genes S100A12, SERPINB2, TIGIT, GRB10, and LHFPL2 in peripheral serum were identified as depression biomarkers by using machine learning algorithms." (PMID 36325528, 2022). "No studies have reported a direct association of S100A12, TIGIT, SERPINB2, GRB10, and LHFPL2 with depression." (PMID 36325528, 2022). "Finally, the results from the three algorithms were combined, yielding S100A12, TIGIT, SERPINB2, GRB10, and LHFPL2 in peripheral blood as depression-related potential biomarkers." (PMID 36325528, 2022).
diabetic retinopathy (1 paper, 2025). "We found that low-dose IL-2 restored the number of TIGIT+ Tregs in diabetic retinopathy." (PMID 40133487, 2025).
disseminated candidiasis (1 paper, 2024). Systemic candidiasis occurs when Candida yeast enters the bloodstream and may spread (becoming disseminated candidiasis) to other organs, including the central nervous system, kidneys, liver, bones, muscles, joints, spleen, or eyes. "Collectively, these findings suggest an association between tissue-resident immune cells, TIGIT expression percentages, and systemic infection, with the absence of TIGIT-KO influencing disseminated candidiasis." (PMID 39109867, 2024).
dysgerminoma (1 paper, 2025). A malignant germ cell tumor characterized by the presence of a monotonous primitive germ cell population. "TIGIT, IDO1, CTLA4, and PDCD1 were specifically upregulated in dysgerminomas." (PMID 40621458, 2025). "Dysgerminomas exhibited an immune-active profile with elevated levels of T cells, CD8+ T cells, and cytotoxic cells, alongside upregulation of immune checkpoints CTLA4, TIGIT, and IDO1, suggesting potential responsiveness to checkpoint inhibitors." (PMID 40621458, 2025).
echinococcosis (1 paper, 2024). A parasitic infection caused by tapeworm larvae of Echinococcus. "Previous studies have indicated that antibiotics (mefloquine and amphotericin B), Chinese herbal medicines (crocin), protease inhibitors (bortezomib and imatinib), and immune checkpoint inhibitors (anti-PD-1/PD-L1 drugs and anti-TIGIT drugs) exhibit anti-echinococcosis effects in animal models." (PMID 39178325, 2024).
endometrial tumor (1 paper, 2021). "TIGIT, another marker of exhaustion, is also expressed by endometrial tumor NK cells." (PMID 33968059, 2021).
epithelioid mesothelioma (1 paper, 2025). "Our study was inspired by the results of the AdvanTG-105 phase I clinical trial, which showed partial response with anti-TIGIT/PD-1 treatment in two epithelioid mesothelioma patients." (PMID 39939955, 2025). "Our study presents evidence of the potent synergy achieved through the combination of anti-PD-1 and anti-TIGIT antibodies, leading to a remarkable 90% response rate, complete tumour rejection, and the establishment of enduring tumour immunity, in this mouse model of epithelioid mesothelioma." (PMID 39939955, 2025).
fibrosis (1 paper, 2023). the formation of excess fibrous connective tissue in an organ or tissue in a reparative or reactive process. "Unlike PD-1, Tim3 and TIGIT were comparably expressed between persons with mild and advanced fibrosis." (PMID 38107019, 2023).
Hashimoto thyroiditis (1 paper, 2019). An autoimmune disorder caused by the production of autoantibodies against thyroid tissue. "Strikingly, the highest levels of TIGIT and PD-1 expression among all tissues included in this study were found in lymph follicles of Hashimoto thyroiditis." (PMID 30733837, 2019). "In inflammatory diseases, the strongest expression of TIGIT/PD-1 was found in Hashimoto thyroiditis." (PMID 30733837, 2019). "It is of note that among all analysed tissues, the highest levels of TIGIT (and PD-1) expression were constantly seen on T helper cells in lymph follicles of Hashimoto thyroiditis." (PMID 30733837, 2019).
Hyperglycemia (1 paper, 2026). An increased concentration of glucose in the blood. "Hyperglycemia seems to reduce the percentage of highly regulatory TIGIT+ Tregs both in vivo and in vitro, and it is associated with reduced glucose consumption by these cells." (PMID 41597269, 2026). "Interestingly, hyperglycemia in in vitro cultures reduced percentages of TIGIT+ Tregs and TIGIT+ Tconvs, and to some extent also CTLA-4+ Tregs." (PMID 41597269, 2026). "Moreover, hyperglycemia, along with low TIGIT+ Tregs levels, results in the induction of immune senescence (negative association between TIGIT+ Tregs and CD57+ Tregs)." (PMID 41597269, 2026). "The negative association between TIGIT+ Tconvs and FAS-L+ Tconvs may suggest that hyperglycemia can inhibit cell apoptosis, leading to the accumulation of unchecked effector T cells and worsening β-cell destruction in diabetic conditions." (PMID 41597269, 2026).
hyperlipidemia (1 paper, 2021). "In conclusion, IL-35 counteracts hyperlipidemia in maintaining Treg-suppressive function by increasing 3 CCR5-amplified mechanisms, including Treg migration, inhibition of Treg weakening AKT-mTOR signaling, and promotion of TIGIT and PD-1 signaling." (PMID 34622804, 2021).
immune deficiency (1 paper, 2025). "The observed decrease in the frequency of TIGIT-positive T cells across all CD4+ subsets may indicate a broader systemic immune deficiency." (PMID 41465029, 2025).
invasive breast carcinoma (1 paper, 2023). A carcinoma that infiltrates the breast parenchyma. "TIGIT is elevated in invasive breast tumor and is closely associated with the prognosis of invasive breast cancer." (PMID 35770416, 2023). "To this end, we analyzed TCGA datasets for the relationship between TIGIT levels in invasive breast cancer and its clinicopathological features." (PMID 35770416, 2023). "Our study shows that TIGIT expression is significantly upregulated in invasive breast cancer and that this correlates with patient prognosis." (PMID 35770416, 2023). "We also found that TIGIT was highly expressed in basal-like and HER2-overexpressing subtypes of invasive breast cancer and used Kaplan-Meier survival analysis to verify the relationship between TIGIT and invasive breast cancer survival." (PMID 35770416, 2023). "We performed a pan cancer analysis of TIGIT expression as well as its expression in invasive breast cancer using a TCGA dataset, and found that TIGIT was significantly upregulated in invasive breast tumor relative to normal tissues, and confirmed this observation using IHC." (PMID 35770416, 2023). "TIGIT may be the target of immunotherapy for invasive breast cancer." (PMID 35770416, 2023). "Therefore, our findings indicate that TIGIT levels may have a significant prognostic value in invasive breast cancer and that it may be a target for invasive breast cancer immunotherapy." (PMID 35770416, 2023).
kidney tumor (1 paper, 2023). "Here we focused on the kidney and discovered a higher expression of TIGIT in kidney tumor with a mean expression of 0.24 in normal kidney and that of 1.47 in kidney tumor." (PMID 37035135, 2023).